ERBB2 (erb-b2 receptor tyrosine kinase 2)
Diseases named in the same sentence as ERBB2 in open-access papers (continued):
Sharing a sentence is not in itself a finding about the gene and the disease.
cancer (continued). "Most of the basal miRNAs targeted factors that have been implicated in the control of luminal biology (FOXA1, ERBB2), adipogenesis (FGFR2, FGFR3) and urothelial differentiation (HOX5/8/13), all of which would be predicted to be suppressed in basal cancers." (PMID 27845906, 2016). "Several studies have shown that endocytic downregulation of ErbB2 is impaired in cancer cells although there is poor understanding of how this is achieved." (PMID 26716506, 2016). "Receptor tyrosine kinases such as EGFR and ErbB2 are overexpressed in many cancers and are being increasingly targeted with targeted drug delivery modalities, including Antibody-Drug-Conjugates (ADCs) and nano-particulate drug delivery systems." (PMID 26859680, 2016). "ErbB3 also plays important roles in cancer, as it dimerizes preferentially with ErbB2 to confer an oncogenic signal." (PMID 27351228, 2016). "In contrast, lysosomal delivery of ErbB2 upon treatment of ErbB2+ cancer cell lines with Trast is distinctly slower and incomplete, apparently due to the maintenance of a recycling itinerary of Trast-bound ErbB2." (PMID 26859680, 2016). "Trastuzumab-DM1 (Kadcyla®, Genentech, San Francisco) is an example of an ADC developed against ErbB2-overexpressing cancers in which a cytotoxic drug (Emtansine) is chemically conjugated to humanized anti-ErbB2 monoclonal antibody Trastuzumab (Genentech)." (PMID 26859680, 2016). "Since the common 17q12-q21 amplicon includes several gene loci, ERBB2-co-amplified genes have been examined for their potential to influence cancer progression and/or therapeutic response." (PMID 27462779, 2016). "The percentage of cells displaying nuclear GLI1 staining positively correlated with ErbB2 positivity (p = 0.027) in the carcinoma samples." (PMID 26843616, 2016). "Female mice transgenic for the activated rat HER-2 oncogene (Neu and ErbB-2 in humans), under the control of the mouse mammary tumor virus promoter, inexorably develop invasive carcinomas in all their mammary glands by the age of six months." (PMID 27486759, 2016). "Because both compounds have been already tested in humans, they provide excellent candidates for validating the concept of dual inhibition of MEK and ERBB2 in more advanced models of KRAS-mutant cancer." (PMID 26018524, 2015). "In fact, several membrane-bound receptor tyrosine kinases (RTKs), such as the EGF receptor and ErbB-2, have been reported in the nucleus of cancer cells (26, –, 28)." (PMID 25623065, 2015). "A similar translocation to the mitochondria was also reported for receptor tyrosine kinase ErbB2 in cancer cell lines and cancer specimens." (PMID 26180580, 2015). "The vast majority of reports describe a pivotal function of ErbB2–ErbB3 heterodimers in cancer cell proliferation or motility." (PMID 26490994, 2015). "Several of the enriched pathways reported herein, i.e., focal adhesion, EGF-EGFR, signaling by ERBB2, angiogenesis etc. have been documented to be of importance not only in human iUC, but in several other human cancers." (PMID 26352142, 2015). "Among 60 genes selected for targeted sequencing, amplifications of the CCND1 and ERBB2 genes were detected in both ctDNA and the primary cancer in this patient." (PMID 26669280, 2015). "In Patient ID-18, amplifications of the CCND1 and ERBB2 genes were suspected in ctDNA and the genes were also clearly amplified in the primary cancer by aCGH analysis." (PMID 26669280, 2015). "As well, combination of MAbs with TKIs, e.g., trastuzumab plus anti-EGFR/anti-ErbB2 such as lapatinib or pertuzumab, revealed of clinical benefit for recurrent cancers following trastuzumab treatment for instance." (PMID 25699077, 2015). "A pathway analysis reveals that the hypomethylation signature includes some of the major pathways that were previously implicated in cancer migration and invasion such as TGF beta and ERBB2 triggered pathways." (PMID 26427334, 2015).
cancer (continued). "A similar association was observed following activation of the PI3K/AKT pathway and resistance to anti-ERBB2 agents in other cancers." (PMID 26267324, 2015). "Third, the hypomethylated genes in our signature are downstream to upstream regulators that have been implicated in cancer metastasis in numerous different studies (e.g., TGFB1, ERBB2)." (PMID 26427334, 2015). "Among NSCLCs, recognized cancer drivers include activating mutations in EGFR, KRAS, BRAF and ERBB2 (HER2), as well as rearrangements of ALK and ROS1." (PMID 26556242, 2015). "Those segments contain well-known oncogenes, including EGFR, SOX2, and ERBB2, which are registered in the Cancer Gene Census database as amplified genes in several types of cancer." (PMID 26465158, 2015). "Pathway analyses identified MAPK/ERBB2 signalling pathways and regulators, and RAS/RAF/ERBB2-dependent cancer-associated pathways as significantly enriched." (PMID 26506417, 2015). "Although the role of the ErbB2/HER2 oncogene in cancers has been extensively studied, how ErbB2 is regulated remains poorly understood." (PMID 25950472, 2015). "Conversely, one of 5 patients with a benign tumor and one of 67 cancer patients had antibodies to ErbB2." (PMID 25889931, 2015). "Remarkably, many EI-containing genes with differential EIS in the ERBB2 sample were shown to play a role in cancer, implying that an impairment of EIS can contribute to carcinogenesis." (PMID 25934563, 2015). "MSI cases are generally characterized by accumulation of mutations in PIK3CA, ERBB3, ERBB2, and EGFR; along with mutations present in ‘hotspot’ sites that have been identified in other cancers." (PMID 26267324, 2015). "As shown in this figure, EGFR and ErbB-3 are primarily expressed in human carcinomas (50% ∼ 70%); ErbB-2 is expressed in 20% ∼ 30% of these carcinomas; and the expression of ErbB-4 occurs only in breast and colon carcinomas." (PMID 25993617, 2015). "Specifically, we examined sensitivity of cancer cells in the presence of mutations and/or over-expression of BRAF, CDH1, ERBB2, CCND1 and MET." (PMID 24884660, 2014). "The EC1-GLuc-p53C exerts its function for ErbB2-targeted bioluminescence and cancer therapy in vitro." (PMID 25190023, 2014). "Activation of ERBB2 and RAS oncogene is known to trigger cell signaling pathways commonly mutated in human cancers." (PMID 24937171, 2014). "The mAb targeting of either EGFR or ERBB2 also generates an increased rate of apoptosis in cancer cells in vitro." (PMID 24970817, 2014). "Overexpression of HER2 (ErbB2/neu) is prognostic of more aggressive disease in several cancers, including breast, gastric, and epithelial ovarian carcinomas 13–15." (PMID 24687970, 2014). "More than half of the genes identified in our previous study of gene regulation by EGFR blockade were significantly modulated upon ErbB2 inhibition in ErbB2-positive cancer cells as well suggesting highly shared oncogenic pathways." (PMID 25238247, 2014). "By contrast, the stromal metagene and the RB-loss signature failed to predict pCR in CL tumors, whereas they predicted pCR in basal and ERBB2-enriched cancers, respectively." (PMID 25277734, 2014). "Obtaining detailed information about the “bad” behavior of ErbB2 can facilitate development of novel treatments against ErbB2-positive cancers." (PMID 24709902, 2014). "Intense efforts have been made to inhibit the activities of the ERBB1/EGFR and ERBB2/HER2 receptors in cancer patients by designing antibodies against the ligand binding domains or small molecules against the tyrosine kinase domains." (PMID 25248370, 2014). "Research on erbB receptors has long been focused on dysregulation of tyrosine kinase activity of EGFR and erbB2 in human cancers." (PMID 24886126, 2014).
cancer (continued). "For example, patients whose cancer cells have an amplification of the ERBB2 (Her2) gene are most likely to benefit from Her2 targeting drugs such as Trastuzumab." (PMID 25233459, 2014). "Antibodies have become an important tool in cancer treatment, and several potentially therapeutic anti-ErbB2 antibodies have been developed." (PMID 25102001, 2014). "The data altogether confirming that TGFβ signaling amplifies oncogenic ErbB2 signaling in vivo and further promotes invasion and metastasis of ErbB2 positive cancer cells." (PMID 24709902, 2014). "The epidermal growth factor receptor 2, ERBB2, is a well-validated target for cancer diagnostics and therapy." (PMID 25089830, 2014). "Several studies have linked ErbB2/Neu overexpression to loss of E-cadherin, a process that is very central for EMT in cancer cells." (PMID 24709902, 2014). "Our studies provide several new avenues to extend the benefits of ErbB2 inhibition in the management of ErbB2-dependent cancers." (PMID 25238247, 2014). "EGFR and pEGFR were nearly absent in glandular epithelial cells of colorectal mucosa adjoining cancer tissue.ErbB2 immunoreactivity was observed in cancer cells in 41 cases (26%; 16% with score 2+ and 10% with score 3+)." (PMID 25416285, 2014). "Overexpression of ErbB2, primarily owing to gene amplification, is observed in many human cancers of epithelial origin including bladder, breast, gastric, lung, ovarian, colorectal, pancreatic, and head and neck cancers." (PMID 24709902, 2014). "Epidermal growth factor receptor (EGFR or HER-1) and its analog c-erbB-2 (HER-2) are protein tyrosine kinases correlated with prognosis and response to therapy in a variety of human cancers." (PMID 24454858, 2014). "Our studies in the aggregate should yield multiple novel ways to expand the benefit of ErbB2 blockade in ErbB2-dependent cancers." (PMID 25238247, 2014). "We then further showed the functional relevance of the T798I ErbB2 mutation as a potential resistance mechanism against reversible ErbB2 inhibitors, modeled by lapatinib, in ErbB2-positive cancer cells." (PMID 25238247, 2014). "EGFR, which shares close structural homology with ErbB2, has been shown to be a client of Hsp90 and has maintained stability in many cancer cells." (PMID 24722501, 2014). "The essential role of ErbB2 in normal cardiac function is demonstrated by ErbB2 knockout mice and by therapeutic targeting of ErbB2 in cancer." (PMID 24709902, 2014). "To analyze the functional relevance of the observed role of the IKK-complex in signalling through B-family plexins, we studied Plexin-B1-mediated signalling in ErbB-2-expressing cancer cells." (PMID 25137062, 2014). "Secondly, SpliceNet and RNASeqNet are evaluated on cancer-specific ERBB2 and MAPK signaling pathways from KEGG database with different number of samples." (PMID 25034693, 2014). "Activation of the survival signaling - PI-3 K/Akt pathway by erbB3 (via interactions with another RTK, particularly erbB2) also gives rise to chemoresistance in cancer treatment." (PMID 24886126, 2014). "In summary, our studies define novel ways of modulating sensitivity and resistance to ErbB2 inhibition in ErbB2-dependent cancers." (PMID 25238247, 2014). "We determined the effects of NOV-002 on ErbB2 activation because ErbB2 has been shown to regulate cell invasion in cancer and is regulated by redox mechanisms." (PMID 24377058, 2013). "The blockade of EGFR and ErbB-2 has been clinically validated as an attractive approach for cancer therapy." (PMID 23936329, 2013).
cancer (continued). "These cancers are usually treated with Trastuzumab, a recombinant antibody designed to block the ERBB2 activity." (PMID 23829771, 2013). "Not surprisingly, therefore, members of the EGFR family, particularly EGFR (also known as ERBB1 or HER1) and ERBB2 (HER2), have been implicated in the development of numerous human cancers and are pursued as therapeutic targets." (PMID 23874846, 2013). "Administration of anti-EGF or optimized anti-Her2/ErbB2 monoclonal antibody (Herceptin/Trastuzumab) are the most widely used—but also very expensive—inhibitors of EGF signaling for the treatment of cancer." (PMID 23531534, 2013). "EMMPRIN is reported to be involved in multidrug resistance of cancer cells via hyaluronan-mediated activation of ErbB2 signaling and cell survival pathway activities." (PMID 24073208, 2013). "In the present study, we designed a novel fusion protein for ErbB2-targeted imaging and cancer therapy." (PMID 24069396, 2013). "The fusion protein EC1-GLuc-p53C efficiently targeted ErbB2-overexpressing cancer cells for bioluminescence imaging and therapy in vitro and in vivo." (PMID 24069396, 2013). "Taken together, these results suggest that the inhibitory effect of EC1-GLuc-p53C on proliferation of cancer cells has an ErbB2-targeting property and is due to the efficacy of p53C peptide in the fusion protein." (PMID 24069396, 2013). "In these patients, the cancer cells are able to overcome the cell cycle arrest mechanisms even though ERBB2 is blocked by Trastuzumab." (PMID 23829771, 2013). "The mechanism of action of monoclonal antibodies toward ERBB2-overexpressing cancer cells include removal of ERBB2 from the cell surface by endocytosis to diminish intracellular signaling, and induction of an immune system-mediated antitumor response." (PMID 23630663, 2013). "The present study showed the utility of a newly constructed protein, EC1-GLuc-p53C, for ErbB2-targeted bioluminescence imaging and cancer therapy in vitro and in vivo." (PMID 24069396, 2013). "Because the level of ErbB2 gene amplification in ErbB2 positive cancers is much higher than in normal tissue, targeted inactivation of the ErbB2 protein evolved as one to the most promising and successful antineoplastic strategies in these cancers." (PMID 23308242, 2013). "Opposite changes in ErbB receptor plasticity have been previously reported for BT474 and SKBR3 mamma carcinoma cells chronically treated with specific anti-ErbB1 and ErbB2 inhibitors." (PMID 23308242, 2013). "They found that all carcinomas in which tyrosine phosphorylated PLC-gamma 1 was present also expressed detectable levels of the epidermal growth factor receptor or erbB-2, two tyrosine kinases known to phosphorylate this enzyme." (PMID 23369435, 2013). "Immediate effects of siRNA on SK-BR-3 growth on the Test Cancer Biochip were observed at day 2 for ERBB2, ESR2, CSK, CTSL2, and BRAF siRNAs." (PMID 23049944, 2012). "ErbB2 antagonists prolong survival in cancer, but also interfere with homeostatic processes in the heart." (PMID 23202898, 2012). "Analyses using the miRanda and Pic Tar algorithms indicated that several cancer-associated genes including MMP11, ERBB2, ERBB3, EDN1, VEGF-A, MMP14 and BCL-9L, were potential target genes of miR-125a." (PMID 22768249, 2012). "Emerging evidence shows that ErbB2 signaling has a critical role in cardiomyocyte physiology, based mainly on findings that blocking ErbB2 for cancer therapy is toxic to cardiac cells." (PMID 22912742, 2012). "Several of the other genes are relevant to cancer—in addition to ERBB2, SKAP1 is an adaptor for Src, DEPTOR regulates the mTOR pathway and NRIP1 is an estrogen-receptor coregulator." (PMID 23260012, 2012). "Aberrant expression and activation of EGFR and ERBB2 (HER2) have been successfully targeted for cancer therapeutics." (PMID 23342251, 2012).
cancer (continued). "The link of ErbB2/HER2 with cancer is also observed in human, as overexpression of the human ErbB2 gene, which encodes the human EGFR (also known as HER2), is related with cancer." (PMID 23209942, 2012). "ErbB2 is overexpressed in a number of human cancers, and humanized anti-ErbB2 monoclonal antibodies are important therapeutic agents in several malignant diseases." (PMID 24281706, 2012). "In cancer cells overexpressing erbB2 due to gene amplification, high basal autophosphorylation of erbB2 promotes oncogenic activities including metastasis and therapeutic resistance." (PMID 22102915, 2011). "In this review we will summarize our strategy to improve the efficacy of a DNA vaccine in preclinical models based on both transplantable ErbB2+ tumors and cancer-prone ErbB2 transgenic mice." (PMID 24212954, 2011). "Mounting evidence has verified that ErbB2 is an important component of the ErbB signaling network in human cancer cells." (PMID 21789172, 2011). "CRM1 is responsible for nucleo-cytoplasmic shuttling of mRNAs and proteins of cancer related molecules including ErbB2." (PMID 21756326, 2011). "In the field of cancer, intrabodies have been used to modulate the expression of proteins upregulated in tumors, such as erbB-2, interleukin-2 receptor, cyclin E (cell cycle protein), and EGFR." (PMID 24212823, 2011). "MUC4 has been shown to act as an unorthodox ligand for ErBB2/HER2, potentiating its responsiveness in cancer signaling." (PMID 21521521, 2011). "A successful example of an approved humanised antibody is represented by Trastuzumab, the only humanised antibody widely used against ErbB2-positive carcinomas for immunotherapy." (PMID 21559015, 2011). "A clinical trial to delay the recurrence of ErbB2+ carcinomas of the oral cavity, oropharynx and hypopharynx is awaiting the approval of the Italian authorities." (PMID 24212954, 2011). "The presence of IBC samples among the 54 ERBB2-amplified tumors reflects the fact that IBCs do comprise a large proportion of ERBB2 cancers." (PMID 20932292, 2010). "Both Erbicin-derived immunoagents (EDIAs) are selectively cytotoxic for ErbB2-positive cancer cells in vitro and vivo, target an ErbB2 epitope different from that recognised by trastuzumab and do not show cardiotoxic effects." (PMID 20051960, 2010). "To test the anti-proliferative effects of anti-ErbB2 immunoagents on cancer cell growth, we treated these cells in soft agar with different doses of immunoagents." (PMID 20051960, 2010). "EGFR is more often related to poor survival of cancer patients, albeit unconsistently, while the ErbB2 prognostic significance remains uncertain." (PMID 24281100, 2010). "For example, of the genes induced by both GFs and augmented by ErbB2, the proto-oncogenic transcription factor MYC has been associated with many forms of cancer often indicating poor prognosis." (PMID 20840765, 2010). "In another study it was suggested that predominantly luminal and HER2 (ERBB2) cancers display a characteristic 'firestorm/amplifier' genomic pattern, that is, when coamplification of many regions in the genome is observed as a common phenomenon." (PMID 20158880, 2010). "These probesets corresponded to 32 known protein coding genes including well known cancer driver genes such as ERBB2." (PMID 20386695, 2010). "RTKs like epidermal growth factor receptor (EGFR) and epidermal growth factor receptor 2 (Her2/ERBB2) are overexpressed or activated in a variety of human cancers." (PMID 21049007, 2010). "We have reported previously that cancer cell invasion induced by overexpression of members of the ErbB tyrosine kinase receptors, including ErbB2, is dependent on FA signalling through FA kinase (FAK)." (PMID 19190626, 2009).